CRP (C-reactive protein)
Diseases named in the same sentence as CRP in open-access papers (continued):
Sharing a sentence is not in itself a finding about the gene and the disease.
anemia (continued). "Laboratory data at onset revealed anemia (hemoglobin, 7.8 g/dL), hypoalbuminemia (albumin, 1.5 g/dL), and elevated serum levels of IgG4 (1080 mg/dL) and CRP (5.05 mg/dL)." (PMID 31951598, 2020). "The typical clinical presentation of iMCD includes fever, general fatigue, anemia, elevated C-reactive protein levels (CRP), and hypergammaglobulinemia." (PMID 33321725, 2020). "Blood biochemical tests do not show any characteristic findings, although high levels of inflammatory response including C-reactive protein (CRP), hypoalbuminemia, and anemia are observed, depending on the activity, nutritional status, and exhaustion level." (PMID 32377946, 2020). "In this study, we demonstrated that male gender, IVIG resistance, anemia, hypoalbuminemia, elevated CRP levels, higher neutrophils count, higher NLR, and higher ALT levels were all risk factors in KD patients who developed CAL." (PMID 32838756, 2020). "According to the results from 42 children patients with TBM, 17 (40.5%) had anemia, while Lactate dehydrogenase (54.8%), Hydroxybutyrate dehydrogenase (64.3%), C-Reactive protein (60.0%) and blood lactates acid (28.6%) were present to different degrees." (PMID 32357835, 2020). "Patients with anemia were older, had a reduced renal function, and had significantly higher levels of inflammatory markers such as CRP or IL-6." (PMID 32751400, 2020). "The two patients with SCD who developed acute chest syndrome, aged 16 and 17 years old, also showed elevated levels of CRP (329 and 66 mg/L, respectively), as well as anemia (8.2 and 7.5 g/dL, respectively)." (PMID 32932612, 2020). "Three sets of blood cultures were drawn, and the initial laboratory investigations revealed mild anemia (haemoglobin 10.8 g/dL), thrombocytopenia (128 G/L) and elevated C-reactive protein (49 mg/L)." (PMID 32306908, 2020). "Initial laboratory investigations revealed neutropenia, thrombocytopenia, normocytic normochromic anemia with high ferritin, elevated liver enzymes and C-reactive protein (CRP)." (PMID 32192451, 2020). "Of 15 cases of moderate/severe anaemia in month 5 or more of treatment and with CRP measurements, only 3 (20%) had inflammation (CRP > 5 mg/L)." (PMID 32139742, 2020). "On lab examinations, he showed only mild increases of erythrocyte sedimentation rate (ESR) and C-reactive protein (CRP), anemia and leukopenia, and inconstant antinuclear antibody positivity." (PMID 33092242, 2020). "The laboratory results showed mild anemia, marked thrombocytopenia and leukopenia and a moderately elevated C-reactive protein." (PMID 32306908, 2020). "Disease activity has been assessed mostly based on clinical symptoms and laboratory findings (anemia, thrombocytopenia or thrombocytosis, hypoalbuminemia, elevated CRP)." (PMID 33255420, 2020). "Three years later (at the age of 20), the patient was admitted to the hospital for fever, elevation of inflammatory markers (including C-reactive protein), progressive splenomegaly, anaemia, leukocytopenia and decreased platelet count." (PMID 32514016, 2020). "Anemia, hypoalbuminemia, increased FC, and elevated CRP were more frequently present in Zn-insufficient patients with IBD." (PMID 32551440, 2020). "Anemia, hypoalbuminemia, C reactive protein (CRP), alanine aminotransferase, neutrophil count, and neutrophil/lymphocyte ratio (NLR) showed significant differences with CAL formation." (PMID 32838756, 2020). "In these studies, the increase in ESR and CRP, anemia, and leukopenia were similar to our case series." (PMID 33167916, 2020). "In our research, according to the univariate and multivariate analysis, advanced ISS stage (ISS stage III), more severe anaemia (Hb < 90 g/L) and elevated CRP (> 10 mg/L) were identified as independent determinants of infection patients with MM." (PMID 32972385, 2020).
anemia (continued). "An increased risk of anemia was associated with surgery for IBD, high inflammatory marker levels such as C-reactive protein, high erythrocyte sedimentation rate, female sex, and use of biological or immunomodulator therapies." (PMID 32898174, 2020). "Conversely, those patients with haematological and biochemical measures consistent with anaemia of inflammation (normal ferritin, raised CRP) appear to have anaemia which is resistant to correction by iron infusion as it is likely caused by other factors." (PMID 32537137, 2020). "All of them had increased C-reactive protein levels, and most of them had elevated erythrocyte sedimentation rate, lymphopenia, anemia, and hypoalbuminemia." (PMID 33167916, 2020). "In ECLIPSE, cachexia was defined as weight-loss > 5% in the past 12 months or low BMI and 3/5 criteria: decreased muscle strength, anorexia, abnormal biochemistry (anemia or high c-reactive protein (> 5 mg/l)), fatigue, and low FFMI." (PMID 32354332, 2020). "Laboratory analyses showed anemia (Hb 8.6 g/dl, normal range 12–16 g/dl) and raised indices of inflammation (C-reactive protein, CRP, 34 mg/L (normal range 0–1 mg/L; Interleukin (IL)-6 158 pg/mL, normal range 0–15 pg/ml)." (PMID 31007844, 2019). "The laboratory results were remarkable for anemia, thrombocytopenia, elevated C-reactive protein (CRP) 21.9 mg/L (reference value ≤ 5 mg/L), and mild transaminitis, with no deranged bilirubin or alkaline phosphatases." (PMID 31228952, 2019). "While he was awaiting elective surgical exploration, he has had two further successive admissions with massive ascites, anemia and raised C-reactive protein with acute kidney injury." (PMID 31967082, 2019). "A distinct biosignature related to anemia was detected, defined by increased values of uric acid, C-reactive protein, and erythrocyte sedimentation rate." (PMID 30718725, 2019). "We compared these five cytokines/GFs concentrations between the patients with and without the negative clinical prognosis factors for MAC-LD (low BMI, low albumin, high CRP and anemia)." (PMID 30885152, 2019). "In laboratory tests that were carried out, she had mild anemia and an increase in C-reactive protein (CRP) level, erythrocyte sedimentation rate (ESR) and lactate dehydrogenase (LDH) level, while other tests were normal." (PMID 30847438, 2019). "Laboratory tests showed that elevated serum ALT/AST, creatinine, and BUN levels were observed in patients with anaplasmosis and coinfection, but elevated serum CRP levels, thrombocytopenia, and anemia were only observed in coinfected patients." (PMID 31539395, 2019). "Laboratory tests reveal elevated ESR-and CRP with thrombocytosis and anemia, occasionally a complement consumption (C3 and C4 low) and circulating immunocomplexes." (PMID 33324879, 2019). "Serum creatinine, brain-derived natriuretic peptide (BNP), C-reactive protein (CRP) and surgical risk scores were higher with increasing severity of anemia." (PMID 30760807, 2019). "Mean serum C-reactive protein was 36.5±24.3 mg/L (range, 0.4–82.9 mg/L), 3 patients had anemia, and 5 patients had hypoalbuminemia." (PMID 30811404, 2019). "Blood results revealed a leucocytosis with a white cell count (WCC) of 13.1, an elevated C-reactive protein (CRP) of 25 mg/L and anaemia (haemoglobin of 107 g/L)." (PMID 31508205, 2019). "Strong prognosis factors identified at baseline are age at diagnosis > 60 years, dcSSc subtype, scleroderma renal crisis, severe dyspnea, FVC and DLCO < 70%, PH, anemia, and CRP > 8 mg/l." (PMID 30944015, 2019). "We lacked data on inflammatory markers including ferritin, IL-6, or C-reactive protein to correlated with degree of anemia or hepcidin levels." (PMID 30925172, 2019). "Risk factors for disease progression include low BMI, cavitary disease on chest CT, number of lung segments involved, older age, male sex, and the presence of comorbidities, as well as anemia, hypoalbuminemia and elevated CRP and/or ESR levels." (PMID 30885152, 2019).
anemia (continued). "We found that increases of 1Log10 in values of both CRP (aOR: 1.36, 95% CI: 1.02–1.81, p = 0.03) and ESR (aOR: 1.04, 95% CI: 1.01–1.06, p = 0.01) at pre-ATT were independently associated with presence of anemia at day 60 of therapy." (PMID 30718725, 2019). "The Swedish primary care depends heavily on POCT CRP testing for workup of patients with suspected infectious diseases and blood cell counts are therefore mainly used for patients with suspected anemia." (PMID 31174471, 2019). "A blood test showed thrombocytopenia, anemia, and elevated C-reactive protein, alkaline phosphatase, and creatinine levels." (PMID 30293532, 2018). "Among TB cases, CRP levels were elevated across groups (varying with anemia status), thus reflecting the stronger inflammatory response in TB patients induced by M. tuberculosis infection." (PMID 29677205, 2018). "Median CRP concentration was significantly lower among controls without anemia than it was among controls with mild and moderate/severe anemia (respectively 0.9 vs. 3.3 vs. 4.1 mg/L, p = 0.024)." (PMID 29677205, 2018). "Patients with missing data were younger and had lower hs-CRP level, systolic BP, and rate of anemia than patients with complete data." (PMID 29338684, 2018). "Her admission bloods showed a white cell count (WCC) of 5.4 × 109 l–1 with a monocytosis, microcytic anaemia, thrombocytopenia and a C-reactive protein (CRP) of 13 mg l−1." (PMID 30931144, 2018). "Laboratory findings include an elevated erythrocyte sedimentation rate, elevated C-reactive protein, microcytic hypochromic anemia, and thrombocytosis." (PMID 30195334, 2018). "In girls with a range of newly diagnosed cancers, including leukaemia, lymphoma, sarcoma, nephroblastoma and neuroblastoma, AMH level was correlated with general health markers, that is, pyrexia, C-reactive protein (CRP) and anaemia." (PMID 30299433, 2018). "Routine blood test showed high leukocyte count (115.27× 109/L), anemia (Hb 84 g/L), a total platelet count of 259 × 109/L, and C-reactive protein (CRP) of 40.9 mg/L." (PMID 29688850, 2018). "A complete blood count revealed anemia with a normal leukocyte and platelet count, a moderate renal insufficiency, hyponatremia, and high C-reactive protein (CRP) concentrations." (PMID 29929552, 2018). "Surgery resulted in anaemia, leucocytosis, lymphopenia, thrombocytosis, rise in neutrophils, CRP, erythrocyte sedimentation rate (ESR) and a reduction in albumin levels." (PMID 29490633, 2018). "Some laboratory parameters such as anemia, hypoalbuminemia, hypercalcemia, and high β2-microglobulin (β2M), C-reactive protein (CRP), creatinine (Cr), and lactate dehydrogenase (LDH) are also prognostically relevant in patients with MM." (PMID 29806594, 2018). "In MM patients, some laboratory parameters including anemia, hypoalbuminemia, hypercalcemia, and elevated β2M, CRP, creatinine, and LDH are related to prognosis." (PMID 29806594, 2018). "The anemia was mild (mean hemoglobin: 11.67±0.79g/dL), ferritin level was significantly low, and C-reactive protein and fibrinogen levels were significantly high in anemic obese patients." (PMID 29666035, 2018). "Some studies demonstrated that anemia was closely related to C reactive protein which is an inflammatory biomarker." (PMID 30139350, 2018). "The risk of anemia gradually and in linear manner decreased with increasing MUAC and hip circumference but it increased with increasing age and CRP level." (PMID 30562390, 2018). "Erythrocyte sedimentation rates (ESR) were increased in all six subjects and serum globulin levels were elevated greatly in 5 cases and 4 patients were presented with mild or moderate anemia and elevated serum C reactive protein (CRP)." (PMID 29740120, 2018). "Among the laboratory parameters, anemia and raised C-reactive protein(CRP) level were present in the majority of patients 65 (64.8%)." (PMID 29881490, 2017).
anemia (continued). "Blood biochemistry is often normal but occasionally elevated CRP, mild anaemia and hypoalbuminemia can be present." (PMID 28610559, 2017). "Prognosis was influenced by biological subtype, extra-skeletal disease extent, severe anemia and abnormal CRP." (PMID 28452680, 2017). "The most common features are elevation of acute phase reactants (ESR, CRP, and thrombocytosis) and a chronic, hypochromic anemia." (PMID 28848544, 2017). "Laboratory tests usually indicate the occurrence of an inflammatory reaction manifesting with anemia, increased white blood cell count, elevated erythrocyte sedimentation rate, and higher expression of C-reactive protein." (PMID 29233162, 2017). "Inour case series, the following factors were related to death: laboratory markers(anemia, increased inflammatory activity: CRP and BNP levels); clinical marker (AF);and imaging (pulmonary artery hypertension)." (PMID 28977057, 2017). "A laboratory analysis showed moderate anemia (hemoglobin 11.0 g/dl), decreased level of total proteins (51 g/L), C-reactive protein (CRP) level reaching 52 mg/L, procalcitonin (PCT) level of 0.79, and erythrocyte sedimentation rate amounting to 95 mm/hour." (PMID 28659187, 2017). "The most frequent laboratory changes were mild anemia with hypoalbuminemia (5/5) and leucocytosis, neutrophilia, panhypoproteinemia and increased CRP (4/5)." (PMID 28728589, 2017). "Subgroup analysis by CKD stage showed that factors associated with anaemia (haemoglobin levels), iron metabolism (TSAT and ferritin levels), and inflammation (CRP levels) were associated with serum hepcidin levels, regardless of CKD stage." (PMID 28652624, 2017). "After a few days of symptomatic home treatment with temporary benefit, he was readmitted showing thrombocytopaenia (PLTs 110 × 109/L), anaemia (Hb 9.2 g/dL) and CRP elevation (40.3 mg/L)." (PMID 28410610, 2017). "Over the following years, she relapsed with acute severe abdominal pain, fever, dramatically elevated CRP, anemia and hypoalbuminemia." (PMID 28610559, 2017). "POCTs should include tests both for identification of patients with severe disease (e.g., severe anemia) and for detection of bacterial infections (such as CRP and PCT)." (PMID 29059253, 2017). "High serum IL-6 related to anemia (P < 0.01), high CRP levels (P = 0.02), severe fatigue (P = 0.02) and hepatic metastasis (P < 0.01)." (PMID 28177923, 2017). "This was, however, not confirmed by laboratory data, which were only notable for elevated CRP, blood sedimentation rate and gammaglobulin, and revealed discrete anemia and slightly increased transaminases." (PMID 28120106, 2017). "There were 9 deaths (10.7%), and the risk factorswere: anemia, BNP and C reactive protein levels, pulmonary hypertension>55 mm Hg, and atrial fibrillation." (PMID 28977057, 2017). "Laboratory data showed anaemia (Hb 7.3 g/dL, requiring blood transfusion even in the absence of symptoms), thrombocytopaenia (PLTs 84 × 109/L) and CRP elevation (40 mg/L)." (PMID 28410610, 2017). "In all PrEP-participants, ID predicted reduced physical performance (adjusted for age, gender, anaemia, serum creatinine, C-reactive protein, LVEF, and NP level)." (PMID 28229219, 2017). "In our trial, CRP was correlated to several factors including other markers of systemic inflammation such as high platelet counts, anemia as well as tumor load and performance status." (PMID 28859644, 2017). "No directional associations were seen between average monthly IV iron dose and 3-month change in C-reactive protein, in contrast with the clear patterns of ‘dose response’ observed for the anemia-related outcomes." (PMID 29121874, 2017). "In our patient, IL-6 accounts for a variety of clinical symptoms including generalized lymphadenopathy and hepatosplenomegaly, polyclonal hypergammaglobulinemia, increased levels of ESR, CRP and ferritin, anemia, and overproduction of autoantibodies." (PMID 28183278, 2017).
anemia (continued). "Several studies have also demonstrated that high levels of IL-6 contribute to the clinical development of anemia and elevated C-reactive protein (CRP) levels." (PMID 28851899, 2017). "Abnormal basic biochemistry levels including anemia, leucocytosis, thrombocytopenia and elevated LDH and CRP were significantly associated with a cancer diagnosis when adjusting for possible confounders." (PMID 29197366, 2017). "Inflammation, as defined by elevated CRP or AGP, was repeatedly associated with anemia in our analysis." (PMID 28615262, 2017). "At the time of entry, lymphopenia (88%), anemia (85%), hypoalbuminemia (49%), plasma C-reactive protein (CRP) elevation (46%), abnormal liver functions (46%), and abnormal renal functions (24%) were observed." (PMID 27703488, 2016). "Among women we found correlations between anemia and several markers of inflammation, such as decreased transthyretin (<0.23 g/L), increased ferritin (>204 μg/L), and increased CRP (≥10 mg/L)." (PMID 27912734, 2016). "Positive FCAL was associated with colonoscopy findings of active IBD (P < 0.05), low albumin (P < 0.05), anemia (P < 0.01), and elevated CRP (P < 0.01)." (PMID 27774443, 2016). "GSE ameliorated inflammation by decreasing CRP, triglyceridemia and counteracted anemia and thrombocytopenia." (PMID 27822171, 2016). "Laboratory examination revealed an elevated inflammatory response with a C-reactive protein (CRP) level of 3.9 mg/dl and anemia with a hemoglobin level of 10.7 g/dl." (PMID 27180251, 2016). "Laboratory tests revealed moderate anemia (hemoglobin: 9.3 g/dl) and elevation of serum C-reactive protein (CRP: 3.19, normal < 0.3 mg/dl)." (PMID 26983443, 2016). "WBC, anemia, CRP, renal function, and hyperglycemia have been reported as independent prognostic factors for AMI." (PMID 27835698, 2016). "Ten (23.3%) patients had a high erythrocyte sedimentation rate, 6patients (13.9%) had a high C-reactive Protein level, and anemia was present in 4 (9.3%)patients preoperatively." (PMID 27849304, 2016). "Laboratory changes reflect the inflammatory process and include elevated ESR and CRP, normochromic normocytic anemia, and hypoalbuminemia." (PMID 27034853, 2016). "In dialysis patients we tested parameters possibly related to the 6-minute walk test result due to their clinical significance as markers of comorbidity, anemia, malnutrition and inflammation: Davies comorbidity grade, hemoglobin, albumin, CRP and TIBC." (PMID 26982967, 2016). "Anemia and disorder of electrolytes are significantly prevalent among preexisting thrombocytopenic patients, with a higher CRP and PCT level." (PMID 26808492, 2016). "Anaemia was diagnosed in all female patients compared to 92% in males, while a positive CRP result was recorded in 90% of females and 72% of males." (PMID 27313944, 2016). "Oral ulceration and involvement within the buccal sulcus are more common in patients with oral CD, as well as an elevated CRP and abnormal full blood count (especially anemia)." (PMID 27017505, 2016). "Sensitivity of LAM increased significantly among participants with a lower Karnofsky Performance score, anemia, hypoalbuminemia, and higher C-reactive protein." (PMID 26865526, 2016). "Once again laboratory analysis showed not only elevated APR (ESR 120 mm, CRP 11.4 mg/dL), but also normochromic normocytic anaemia (haemoglobin 11.6 g/dL) and hypoalbuminemia (albumin 3.0 g/dL)." (PMID 27034853, 2016). "Anaemia, phosphocalcium metabolic disorders, and a positive CRP result among haemodialysed patients were estimated at 94.3%, 61.6%, and 77.1% respectively." (PMID 27313944, 2016). "Common laboratory anomalies include anemia, hypoalbuminemia, polyclonal gammopathy, elevated erythrocyte sedimentation rate or C-reactive protein concentration, and proteinuria." (PMID 27313621, 2016).